SLC52A3 (solute carrier family 52 member 3)
Description:
Plasma membrane transporter mediating the uptake by cells of the water soluble vitamin B2/riboflavin that plays a key role in biochemical oxidation-reduction reactions of the carbohydrate, lipid, and amino acid metabolism. Humans are unable to synthesize vitamin B2/riboflavin and must obtain it via intestinal absorption.
Synonyms: hRFT2; C20orf54; RFT2; RFVT3; bA371L19.1; BVVLS; BVVLS1
Tractability: Antibody: UniProt places it where antibodies can reach, with high confidence; its Gene Ontology location is reachable by antibodies, with high confidence; UniProt predicts a signal peptide or a membrane-spanning region.
Gene: Protein-coding gene on chromosome 20 (758,695 to 776,015, reverse strand). Ensembl gene ENSG00000101276.
Subcellular location: Apical cell membrane; Cell membrane; Cell membrane (Isoform 1); Nucleus membrane; Cytoplasm; Cytoplasm (Isoform 2)
Pathways (Reactome):
Metabolism: Vitamin B2 (riboflavin) metabolism
Gene Ontology:
Molecular function: protein binding; riboflavin transmembrane transporter activity
Biological process: riboflavin transport; sensory perception of sound; riboflavin metabolic process
Cellular component: apical plasma membrane; cytoplasm; nuclear membrane; plasma membrane
Genetic constraint (gnomAD): Loss-of-function variants: 23 observed, 32.2 expected, observed/expected ratio (o/e) 0.71, 90% interval 0.51 to 1.01. The upper end of that interval is the gene's LOEUF score, 1.01, which puts it in group 4 of 6, group 1 being the genes least tolerant of losing a copy. Missense variants: 548 observed, 618.38 expected, observed/expected ratio (o/e) 0.89, 90% interval 0.82 to 0.95. Synonymous variants: 301 observed, 275.73 expected, observed/expected ratio (o/e) 1.09, 90% interval 0.99 to 1.2.
Gene-disease validity (ClinGen):
ClinGen rates the evidence that SLC52A3 causes each of these diseases.
Brown-Vialetto-van Laere syndrome 1 (autosomal recessive): Definitive. Any Brown-Vialetto-van Laere syndrome in which the cause of the disease is a mutation in the SLC52A3 gene.
Homologues: Orthologues: chimpanzee SLC52A3 (99% identical), macaque SLC52A3 (97% identical), pig SLC52A3 (82% identical), dog SLC52A3 (82% identical), guinea pig SLC52A3 (78% identical), mouse Slc52a3 (74% identical), rat Slc52a3 (66% identical), zebrafish slc52a3-1 (53% identical), tropical clawed frog slc52a3 (52% identical), Drosophila melanogaster Rift (35% identical), Caenorhabditis elegans rft-1 (31% identical), Caenorhabditis elegans rft-2 (31% identical). Paralogues in human: SLC52A2 (39% identical), SLC52A1 (39% identical).
Diseases named in the same sentence as SLC52A3 in open-access papers:
SLC52A3 is named in the same sentence as 49 diseases in open-access papers, as found by Europe PMC text mining. Sharing a sentence is not in itself a finding about the gene and the disease. The quoted sentences say what the papers report.
Brown-Vialetto-Van Laere syndrome (12 papers, 2014 to 2025). "In 2010, mutations SLC52A2 (encoding RFVT2) and SLC52A3 (encoding RFVT3) were shown to cause the neurodegenerative disorder Brown-Vialetto-Van Laere syndrome (BVVL) which, therefore, designated it as a riboflavin transporter deficiency (RTD)." (PMID 33036493, 2020). "Loss-of-function mutations in two riboflavin transporter genes, SLC52A2 and SLC52A3, have recently been linked to Brown-Vialetto-Van Laere syndrome." (PMID 29053833, 2017). "The mutation of SLC52A3 may cause degenerative disorders like Brown-Vialetto-Van-Laere syndrome (BVVL) and Amyotrophic lateral sclerosis (ALS)." (PMID 33228685, 2020). "Early onset weakness in the upper limbs and neck is almost invariably seen in patients with mutations in SLC52A2, in contrast to those patients with SLC52A3 mutations or genetically unclassified Brown-Vialetto-Van Laere syndrome, in whom the onset of weakness is often more generalized." (PMID 24253200, 2014). "Another distinctive feature of patients with SLC52A2 mutations is a lack of upper motor neuron signs in the lower limbs, a commonly reported clinical feature of Brown-Vialetto-Van Laere syndrome and, in particular, reported in patients with mutations in SLC52A3." (PMID 24253200, 2014). "Fazio–Londe syndrome is a condition similar to BVVL that presents with the same symptoms, except for hearing loss, and it is related to mutations in the SLC52A3 gene located on chromosome 20p13, which encodes the intestinal riboflavin transporter (hRFT2)." (PMID 39457470, 2024). "Recessive mutations in the SLC52A3 gene can also result in Brown-Vialetto-Van Laere syndrome; however, there are differences in the phenotype of patients harbouring SLC52A2 mutations compared with the phenotype of patients with SLC52A3 mutations." (PMID 24253200, 2014). "RF transporter deficiency (RTD; also known as Brown-Vialetto-Van Laere syndrome) is a progressive inherited neuropathy with childhood onset, caused by mutations in SLC52A2 (RTD2) or SLC52A3 (RTD3), which encode the human RF transporters 2 (RFVT2) and 3 (RFVT3), respectively." (PMID 40684659, 2025). "Riboflavin transporter deficiency (RTD, OMIM 614707), formerly known as Brown‐Vialetto‐Van Laere (BVVL) or Fazio Londe syndrome (OMIM 211500) is an inborn error of metabolism caused by variants in SLC52A2 or SLC52A3, encoding the human riboflavin transporters RFVT2 and RFVT3, respectively." (PMID 38974615, 2024). "A disorder with a similar presentation, but without deafness, is Fazio-Londe syndrome, which is caused by mutations in SLC52A3 and is now included in the RTD disease spectrum." (PMID 33036493, 2020). "Brown-Vialetto-Van Laere Syndrome (BVVLS), a rare neurological disorder characterized by motor, sensory, and cranial neuronopathies, is mainly associated with defective riboflavin transporters encoded by SLC52A2 and SLC52A3 genes." (PMID 31064337, 2019). "Brown-Vialetto-Van Laere syndrome is a rare disorder characterized by motor, sensory, and cranial neuronopathies, associated with mutations in SLC52A2 and SLC52A3 genes that code for human riboflavin transporters RFVT2 and RFVT3, respectively." (PMID 28856173, 2017). "Thus far, three separate subtypes of RTD2 are described—type 1, 2 and 3—but, previously, RTD was classified as two separate genetic defects: Brown–Vialetto–Van Laere syndrome and Fazio–Londe syndrome, caused by mutations in the SLC52A2 and SLC52A3 genes, respectively." (PMID 41295274, 2025).
esophageal squamous cell carcinoma (8 papers, 2013 to 2026). Esophageal squamous cell carcinoma (ESCC) is a type of esophageal carcinoma (EC) that can affect any part of the esophagus, but is usually located in the upper or middle third. "Recently, two SLC52A3 transcript variants that differ in the transcriptional start site, were described in esophageal squamous cell carcinoma (ESCC), named SLC52A3a and SLC52A3b." (PMID 32722651, 2020). "SLC52A3 was recently identified as a susceptibility gene for esophageal squamous cell carcinoma (ESCC)." (PMID 27472962, 2016). "Importantly, aberrant expressions of SLC52A3 are associated with stepwise development of esophageal squamous cell carcinoma (ESCC) as well as the survival rates of ESCC patients." (PMID 29428966, 2018).
esophageal cancer (4 papers, 2016 to 2022). A primary or metastatic malignant neoplasm involving the esophagus. "NF-κB p65/Rel-B can activate the expression of SLC52A3, and SLC52A3 was identified as a novel therapeutic target for esophageal cancer." (PMID 36253873, 2022). "In a previous study, SLC52A3 was identified as a prognostic biomarker in esophageal cancer." (PMID 32685482, 2020).
glioma (4 papers, 2018 to 2021). A benign or malignant brain and spinal cord tumor that arises from glial cells (astrocytes, oligodendrocytes, ependymal cells). "Previous studies also found that SLC52A3 rs13042395 C > T change could promote glioma cancer cell progression and migration in vivo and in vitro." (PMID 32888389, 2020). "Moreover, SLC52A3 enhanced the proliferation of ESCC and glioma cells." (PMID 29428966, 2018). "It was also reported that SLC52A3 is upregulated in ESCC and glioma, compared with nonmalignant adjacent tissue." (PMID 29428966, 2018).
gastric cancer (3 papers, 2013 to 2020). A primary or metastatic malignant neoplasm involving the stomach. "In our research, we found that SLC52A3 rs13042395 C > T variation was significantly associated with poor survival in a 926 Chinese gastric cancer (GCa) patients cohort (CC/CT genotype versus TT genotype, HR = 0.57, 95%CI (0.40‐0.82), log‐rank P = 0.015)." (PMID 32888389, 2020). "To explore the role of SLC52A3 in regulating malignant phenotype of gastric cancer cells, including cell proliferation, colony formation, migration and invasion, we established stable transfected gastric cancer cell lines with MGC803 and AGS." (PMID 32888389, 2020). "To further explore the role of GJA1 in SLC52A3‐mediated malignant phenotype, we co‐transfected GJA1 in SLC52A3‐expressing MGC803 and AGS gastric cancer cells and detected GJA1 expression level by Western blotting." (PMID 32888389, 2020).
hearing loss (2 papers, 2023 to 2025). "Mutations in the SLC52A3 gene (also known as BVVLS, BVVLS1, C20orf54, RFT2, RFVT3, bA371L19.1, hRFT2) are associated with the neurological and motor disorders characteristic of BVVLS, occurring mainly with progressive ponto-bulbar palsy and hearing loss." (PMID 39922111, 2025).
hyperlipidemia (2 papers, 2016 to 2019). "Knockout of Slc52a3 in mice caused reduced riboflavin concentrations in pups resulting in death, with signs of hyperlipidemia and hypoglycemia." (PMID 30925895, 2019). "We demonstrated for the first time that Rfvt3 contributes to placental riboflavin transport, and disruption of Slc52a3 caused neonatal lethality with hyperlipidemia and hypoglycemia owing to riboflavin deficiency." (PMID 27272163, 2016). "Disruption of Slc52a3 caused neonatal lethality with hyperlipidemia and hypoglycemia attributable to riboflavin deficiency." (PMID 27272163, 2016). "Most Slc52a3−/− mice died with hyperlipidemia and hypoglycemia within 48 hr after birth." (PMID 27272163, 2016).
Hypoglycemia (2 papers, 2016 to 2019). A decreased concentration of glucose in the blood. "Newborn Slc52a3−/− mice exhibited hypoglycemia, although transplacental transport of glucose in Slc52a3−/− pups was not changed." (PMID 27272163, 2016).
Ataxia (1 paper, 2025). Ataxia refers to impaired coordination of voluntary muscle movement. "Translational concordance is strong: zebrafish SLC52A3 knock-down and SLC52A3−/− mice recapitulate hearing loss, ataxia and early death, all of which improve with systemic riboflavin supplementation." (PMID 40963932, 2025).
auditory neuropathy (1 paper, 2020). A hearing disorder characterized by impaired transmission of signals through the auditory nerve, resulting in mild to severe hearing loss and poor speech perception. "Only one heterozygous SLC52A3 mutation was detected, but presence of a sub‐clinical auditory neuropathy and dramatic improvement under high dose riboflavin argued for a RTD." (PMID 32022482, 2020).
axonal neuropathy (1 paper, 2024). Any nerve disorder affecting the axon of a nerve. "A nerve conduction study revealed axonal neuropathy, while molecular analysis revealed a homozygous mutation in one of the riboflavin transporter genes, SLC52A3, confirming BVVL syndrome." (PMID 38745833, 2024).
Childhood onset (1 paper, 2020). Onset of disease at the age of between 1 and 5 years. "This is a rare, childhood-onset disease characterized by motoneuron degeneration and caused by mutations in SLC52A2 and SLC52A3, encoding riboflavin (RF) transporters (RFVT2 and RFVT3, respectively), resulting in muscle weakness, ponto-bulbar paralysis and sensorineural deafness." (PMID 33036493, 2020).
multiple acyl-CoA dehydrogenase deficiency (1 paper, 2016). "Accordingly, three patients with SLC52A3 mutation exhibited increased plasma acylcarnitines and urine organic acids, and mimicked an inherited disorder affecting mitochondrial fatty acid β-oxidation: i.e. multiple acyl-CoA dehydrogenase deficiency (MADD)." (PMID 27272163, 2016).
polydactyly (1 paper, 2024). A disease characterized by the presence of polydactyly, including syndromic and non-syndromic forms. "Combined with the results of genome-wide association studies, we identified candidate genes associated with the crest (SMYD and STOX2) and polydactyly (SLC52A3 and ANGPT4)." (PMID 38612286, 2024). "A total of 151 SNP loci significantly correlated with the polydactyly trait were identified through GWAS, and five genes, R-spondin 4 (RSPO4), tensin-3 (TNS3), chloride channel 7 (CLCN7), SLC52A3, and ANGPT4, were annotated to be significantly correlated with polydactyly." (PMID 38612286, 2024). "Furthermore, three genes affecting the development of polydactyly, angiopoietin 4 (ANGPT4), histocompatibility minor 13 (Hm13), and solute carrier family 52 member 3 (SLC52A3), were identified by overlap analysis." (PMID 38612286, 2024). "SLC52A3 and ANGPT4 genes might play an important role in the formation of the polydactyly of the Taihu Dianzi pigeon." (PMID 38612286, 2024).
tumor (9 papers, 2013 to 2023). "SLC52A3 has been implicated in the biology of several tumor types, including those from stomach and cervix." (PMID 29428966, 2018). "However, associations between the single nucleotide polymorphisms (SNPs) rs13042395 (C > T) and rs3746803 (G > A) in SLC52A3 and risk, tumor characteristics and survival of ESCC patients remain inconclusive and of unknown prognostic significance." (PMID 27472962, 2016). "In the present study, we investigated the association between rs13042395 or rs3746803, in SLC52A3, and ESCC risk, tumor characteristics and survival." (PMID 27472962, 2016). "Similarly, to SLC44A4, the upregulation of SLC52A3 was observed in more than half of TCGA tumor types when compared to pooled GTEx control group." (PMID 37397501, 2023). "Conversely, the promoter region of the SLC52A3 showed a negative correlation with its expression levels in at least 12 tumor types, except for cg20494450." (PMID 37397501, 2023).
cancer (5 papers, 2018 to 2024). A tumor composed of atypical neoplastic, often pleomorphic cells that invade other tissues. "Nevertheless, the detrimental role of riboflavin and its associated transporters, namely SLC52A2 and SLC52A3, in cancer has been extensively characterized." (PMID 38430255, 2024). "More importantly, our findings identify SLC52A3 as both a predictive and prognostic biomarker for this deadly cancer." (PMID 29428966, 2018). "Interestingly, abnormal expression patterns of SLC52A3 in multiple types of human cancers have been recently noted." (PMID 29428966, 2018).
neurological disorder (5 papers, 2017 to 2025). "Our findings draw important parallels with RF transporter deficiency disease (RTD), a neurological disorder caused by mutations in SLC52A2 (RTD2) or SLC52A3 (RTD3) that manifests in infancy." (PMID 40684659, 2025).
metabolic disorder (2 papers, 2020 to 2025). "Our previous study demonstrated that Slc52a3 knockout (Slc52a3−/−) mice exhibited neonatal lethality and metabolic disorder due to riboflavin deficiency." (PMID 33116204, 2020).
adenocarcinoma (1 paper, 2020). A common cancer characterized by the presence of malignant glandular cells. "While in the GCa, as 90% of them were adenocarcinoma, SLC52A3 rs13042395 C > T change played a consistent role as an oncogene both in risk or survival analysis and in our present mechanism studies." (PMID 32888389, 2020).
neurodegenerative disease (1 paper, 2022). A disorder of the central nervous system characterized by gradual and progressive loss of neural tissue and neurologic function. "This childhood-onset neurodegenerative disease is caused by biallelic pathogenic variants in either SLC52A2 or SLC52A3 genes, resulting in insufficient supply of riboflavin (vitamin B2) and consequent impairment of flavoprotein-dependent metabolic pathways." (PMID 35740351, 2022).
SLC52A3 also shares sentences with these, for which no sentence is quoted: optic atrophy (3 papers); melanoma (2); amyotrophic lateral sclerosis (1); breast carcinoma (1); breast tumor (1); cervical cancer (1); Charcot-Marie-Tooth disease type (1); colorectal cancer (1); cranial neuropathies (1); deafness (1); diabetes (1); Encephalopathy (1); esophageal adenocarcinoma (1); Fazio–Londe disease (1); Friedreich ataxia (1); gastrointestinal disease (1); hereditary spastic paraplegia 7 (1); lymph node metastasis (1); neuropathy (1); oesophageal cancer (1); ovarian carcinoma (1); ptosis (1); Respiratory insufficiency (1); Sensorimotor neuropathy (1); sensory ataxia (1); spinal muscular atrophy (1); Visual impairment (1); Vocal cord paralysis (1); Wilson disease (1).